MKI67 (marker of proliferation Ki-67)
Diseases named in the same sentence as MKI67 in open-access papers (continued):
Sharing a sentence is not in itself a finding about the gene and the disease.
tumor (continued). "Genes specifically upregulated in the high mRNAsi group included MKI67, MGST1, and ALOX5AP, which are associated with lipid metabolism, endoplasmic reticulum stress, and tumor progression." (PMID 40963856, 2025). "Violin plots effectively illustrated the expression levels of these regulatory modules among tumor subpopulations, with C2 MKI67+ TCs exhibiting the highest expression in M3, succeeded by C0 NAP1L1+ TCs." (PMID 40842994, 2025). "Immunohistochemistry assays revealed that treatment with MS159 resulted in a striking decrease of cell proliferation marker MKI67/Ki-67 in the tumor xenografts." (PMID 40097917, 2025). "It is revealed that MKI67 expressed in 38 immune cell subtypes generally significantly contributed to the level of tumor-infiltrating immune cells in several cancer types." (PMID 40070823, 2025). "The analyses revealed that GSH metabolism-related genes exhibited significantly higher expression in tumor tissues, particularly within myeloid cells, NK/T cells, B cells, and MKI67+ cells, compared to normal pancreatic samples." (PMID 40375987, 2025). "The cell cycle analysis revealed an induction of G0/G1-S transition in tumor cells by stress stimuli, which was validated by the expression profiling analysis of Mki67 in tumor cells." (PMID 40670350, 2025). "Next, we analyzed the MKI67 protein-protein interaction using the String database to further explore the probable molecular mechanisms of it in tumor prognosis." (PMID 40070823, 2025). "High expression of MKI67 is indicative of increased proliferative activity and is often correlated with aggressive tumor behavior." (PMID 38250721, 2024). "The CD4_C5_MKI67 cluster was highly proliferative, suggesting active cell division and a positive response to tumor antigen-specific stimuli, making them potential immunotherapy targets." (PMID 38720887, 2024). "Even after taking into account tumor grade and MKI67 expression level as confounding covariates, patients with high expression levels of both genes had a significantly higher risk of relapse than those with low expression levels." (PMID 38254664, 2024). "Lastly, MKI67 expression in GrB+ B cells was analyzed to assess the impact of clonal expansion in tumor samples." (PMID 38386050, 2024). "We extracted and re‐clustered ICC tumor cells and named those overexpressing MKI67, TOP2A, and UBE2C as proliferating tumor cells (Prolif)." (PMID 39716897, 2024). "Of which a proliferative cell lineage named C1QC+MKI67+TAMs was recognized with high immunosuppressive capacities, suggesting it has immune suppression and cell proliferation functions in the tumor niche." (PMID 39323622, 2024). "The results indicated that the MKI67+ cells represented the proliferative populations contributing to the oestrogen‐dependent tumour growth." (PMID 38282415, 2024). "It was observed that the pBADSer99 level was not related to age nor lymph node metastasis, but was positively correlated with lower tumor grade and higher MKI67 labeling." (PMID 38200104, 2024). "We demonstrated that the increase in Pcna expression was observed only in the SH mice in both the tumor tissue and peritumoral area, and Mki67 expression increased only in the peritumoral area." (PMID 39063041, 2024). "In iPSCs, the strongest reaction was the tumor-proliferation signature of MKI67+ progenitor cells, while the weakest reactions were the TGFB pathway and the cellular response to hypoxia of nerve cells." (PMID 39699375, 2024). "The expression of MKI67 represents the state of cell proliferation and plays an important role in tumor migration, invasion, and progression." (PMID 38464517, 2024). "As expected, the tumor mutation burden (TMB) and ki-67 index/MKI67 mRNA expression in the ICold subtype were comparable to or higher than what was seen in the IHot subtype." (PMID 39531335, 2024).
tumor (continued). "It has been confirmed that tumor proliferation-related markers MKI67 and PCNA (proliferating cell nuclear antigen) are closely related to the differentiation, invasion, and metastasis of many tumors." (PMID 38402311, 2024). "The combination of neoantigen vaccines with bevacizumab and immune checkpoint inhibitors (ICIs) significantly enhances the enrichment of neoantigen-specific Mki67 T cells within tumor, thereby improving anti-tumor immune responses." (PMID 38280084, 2024). "As resident tumor macrophages expressing MKI67, CDK1, and CDC45, HMGB1, and others, Prolif-TAMs were likely pro-inflammatory, profibrotic, and promoting tumor progression." (PMID 39184073, 2024). "As expected, OPC markers OLIG2, SOX9, and cell cycle genes CDK1, MKI67 are highest in the tumor core (early peak), while neuronal markers ZIC1, GABRA1, and mature oligodendrocyte marker MBP are highest in the GCL_N (late peak)." (PMID 36823172, 2023). "Mutations in MKI67 and YWHAE were undetectable in primary tumour regions in P035 but were clonally dominant in LNmet." (PMID 38009315, 2023). "Using MKI67 as a marker of proliferating tumour cells, we validated the spatially restricted response of drug-treated PDOX to Palbociclib." (PMID 37127652, 2023). "Tumor sections also had increased Ki-67 (also known as MKI67) and Alcian Blue staining compared to control sections." (PMID 36579622, 2023). "Noteworthy, our pituisphere experiments showed that incubation in octreotide and cabergoline reduce expression levels of Ki-67 (MKI67) which is one of widely used markers in histology to assess tumour proliferation capacity therefore also aggressiveness." (PMID 36774501, 2023). "The pathological features important for predicting the DFS and OS hazard risks included mesenchymal expression profile of gene expression, FIGO stage IV, tumor grade 3, and MKI67 proliferation marker expression (p < 0.001)." (PMID 37628927, 2023). "The cell proliferation antigen MKI67 is a widely used marker in tumor histopathology, and the high expression of MKI67 in phenotype_B confirmed the hyperactive proliferation activity." (PMID 35635121, 2023). "Subgroup 1 exhibited elevated expression levels of cell cycle genes PCNA and MKI67, as well as the tumor stem cell marker CD44." (PMID 37608794, 2023). "The spatial gene expression profile validated that tumor tissues expressed high levels of Pcna and Mki67, two cellular proliferation markers." (PMID 37414763, 2023). "This interpretation is consistent with higher gene expression of effector- and division-associated genes (GZMB, IFNG, MKI67) in the untreated tumor and low expression of activation markers such as HLA-DR and CD38 in the irradiated tumor." (PMID 37209684, 2023). "In seven of the 14 TCGA cancer types, high-TMB cancers displayed significantly higher expression levels of MKI67, a marker for tumor cell proliferation, and proliferation signature scores than low-TMB cancers (two-tailed Student’s t test, P < 0.1)." (PMID 36911742, 2023). "In all five ccRCC tumors analyzed by targeted scRNAseq, expression of MKI67 was primarily observed in T-cell clones found exclusively in tumor for every case." (PMID 36185254, 2022). "The density of proliferating CD8+ T-cells (MKi67+CD8+) in tumor sections is a commonly used measure of immune activation and is positively associated with a good prognosis across several cancer indications." (PMID 35558070, 2022). "A slowed tumor progression or a significantly increased apoptosis was reported upon MKI67 knockdown/knockout in several cancer cells lines." (PMID 36500393, 2022). "Clinical immunohistochemical data showed that the expression of tumor marker (MKI67) in cancer tissues was stronger than that in normal tissues." (PMID 35449547, 2022). "TIMER database analysis confirmed that CTSV and MKI67 were highly expressed in tumour tissues, while CXCL8 and PRF1 were expressed at low levels in tumour tissues, which was consistent with our findings." (PMID 35902905, 2022).
tumor (continued). "The gene expression levels of Erb-B2 receptor tyrosine kinase 2 (ERBB2) and MKI67 from Select-seq were in agreement with the corresponding RNA in situ hybridization results in serial sections of the same tumour." (PMID 35534484, 2022). "Our analyses of both the targeted and high-throughput whole transcriptome scRNAseq data sets demonstrated that the proliferation marker MKI67 was primarily expressed on expanded, tumor-restricted TCR clonotypes." (PMID 36185254, 2022). "Compared with expanded T-cell clonotypes that were found in two or more tissues, expanded T-cell clones that were exclusively found in tumor demonstrated elevated expression of the proliferation marker MKI67 and the antigen-induced marker CTLA4." (PMID 36185254, 2022). "We first compared the ratio of SOX9/MKI67-positive cells in normal and tumor tissues in vivo and primary tumor-derived organoid in vitro." (PMID 35974387, 2022). "We found an upregulation of 5p‐end genes including TERT in TCGA tumours with high MKI67 expression, supporting our findings." (PMID 35979662, 2022). "GEPIA database analysis showed that RNASEH2A and HENMT1 were positively correlated with the expression of tumor marker (MKI67)." (PMID 35449547, 2022). "Consistent with the observed increased proliferative differences, we noted prominent Mki67+/Ly6d+ cells in our mouse scRNA-Seq data and subsequently found Edu incorporation of Ly6d+ cells from the tumor are more significant than from the normal epidermis." (PMID 36473848, 2022). "The highest concentration of genistein negatively affected the expression of the MKI67 in both tumor cells and dermal fibroblasts." (PMID 36293214, 2022). "We compared levels of FoxP3+ and MKi67+CD8+ cell densities (counts/mm2) from >1000 baseline tumor samples from clinical trials and commercially available sources." (PMID 35558070, 2022). "According to previous reports, the functions of CD44, ADM, TYMS, and MKI67 are primarily in promoting the Warburg effect and tumor growth in various cancers, while the function of those four genes in DTC has rarely been reported." (PMID 35528004, 2022). "Based on literature findings, the expression of MKI67 gene was significantly correlated with lymph node metastases, tumor invasion and adverse survival outcome in TNBC." (PMID 36497286, 2022). "As evidenced by IHC staining, the expression levels of KIF20A, MMP-2, MMP-9 and MKI67 increased significantly in tumor tissues in the KDELR2 overexpression group." (PMID 36096734, 2022). "Results were confirmed by RT-qPCR analysis of Mki67 mRNA levels, showing a significantly higher proliferation rate in Myc-R26Met compared with Alb-R26Met tumours." (PMID 36433941, 2022). "While MKI67 staining revealed several regions with different IF intensity in tumor tissue, staining intensity was homogenous and low in healthy tissue." (PMID 35328369, 2022). "Most tumors showed a positive correlation between CD45 and MKI67 expression suggesting that high CD45 expression is indicative of a tumor microenvironment that promotes tumor cell proliferation and cancer progression." (PMID 36061172, 2022). "They classified tumor cells into three categories: high expression of MKI67, high expression of miR-17, and high expression of MKI67 and miR-17." (PMID 35590346, 2022). "Similar to B-ALL, we also found that this population of T cells highly expressing ITGAE and MKI67 was elevated in the tumor microenvironment of multiple solid tumors." (PMID 36532049, 2022). "It was found that HENMT1 and RNASEH2A were positively correlated with the expression of tumor marker (MKI67)." (PMID 35449547, 2022). "Cluster 3 in Paratumor and Cluster 6 in Tumor had proliferating cells (MKI67+) of various lymphocyte lineages." (PMID 33429363, 2021). "We analysed the association of MKI67 levels with TIIC gene markers in LIHC based on GEPIA2 and TIMER to reveal the underlying relationship of MKI67 expression with tumour immune infiltration degree." (PMID 34724892, 2021).
tumor (continued). "The most frequent top mutated genes in tumor fragments of women were USH2A, ATM, IGF2R, MKI67, and MAP3K1 (median variants per sample = 20; missense, nonsense, and splice site mutations)." (PMID 34680380, 2021). "Meta-program A was characterized by markers of the cell cycle, such as Top2a and Mki67, indicating the presence of proliferating subpopulations of tumor cells in all tumors." (PMID 34210306, 2021). "MKI67-related functional networks and genomic alterations within LIHC were evaluated based on multidimensional analysis, where the function of MKI67 in tumour immunity was also explored." (PMID 34724892, 2021). "MKI67, the well-characterized proliferation markers, were found heavily enriched for radioresistant and stem-like tumor cells." (PMID 34066132, 2021). "For example, the smaller cell cluster B4b was a highly proliferative tumor with cells at either the G2/M, or S phase and displayed high expression of MKI67, CDK4, and other proliferative markers such as PCNA, TK1, and TYMS." (PMID 34001881, 2021). "For example, the smaller cell cluster B4b was a highly proliferative tumor with cells at either the G2/M, or S phase (right two panels) and displayed high expression of MKI67, CDK4, and other proliferative markers such as PCNA, TK1, and TYMS." (PMID 34001881, 2021). "The antigen KI-67, as encoded by the MKI67 gene, is a critical cell proliferation-related biomarker and has been used clinically as a prognostic indicator of tumor recurrence and clinical outcome." (PMID 34895070, 2021). "When comparing the expression of the proliferation marker MKI67 between the normal and cancer samples, the tumor samples had significantly higher expression (fold change = 2.22, p = 0.0001)." (PMID 34408238, 2021). "Increased levels of GITR, TNFSF4 (OX40L), and 4-1BB suggest activation, while increased MKI67 expression identifies cluster 4 as the most proliferative cluster in the tumor." (PMID 33602930, 2021). "The tumour growth advantage was also supported by the upregulation of pAKT1, pMTOR, pRPS6, pEIF4EBP1, MKI67, MYC and HK2 and the downregulation of hsa‐miR‐429." (PMID 34954904, 2021). "Tumors from MUP-uPA mice fed the HFHC diet exhibited an increased expression of tumor markers Ly6d, Cd44, Golm1, and Birc5, as well as higher levels of the proliferation marker Mki67." (PMID 34439245, 2021). "Tumours collected from mice at diestrus exhibited a significant increase in the expression of genes Mki67 (p = 0.05), Ccnb1 (p = 0.02), Erbb2 (p = 0.03), Grb7 (p = 0.02), and Bag1 (p = 0.05), compared to tumours collected at estrus." (PMID 34174867, 2021). "We then further demonstrated that PtpA contributes to MKI67-mediated tumor cell proliferation, migration, and invasion during Mtb infection." (PMID 33097805, 2020). "Enumeration of these four classes across multiple micrographs per tumor type revealed a statistically significant reduction in double-positive (MKI67+,HIF1a+) cells in ALK4L75A-Fc-expressing tumors." (PMID 33187540, 2020). "Applying this approach to phenotypes, we identified oncogenic and tumor-suppressor genes and enhancers, by simply testing their associations with MKI67 (Ki-67), a commonly used proliferation marker." (PMID 31980032, 2020). "Then, to assess how the predicted expression of MKI67 varies within each sample, we calculated the AUC for distinguishing tiles located in the tumor from those located in the healthy tissue for every given slide." (PMID 32747659, 2020). "Ki-67 nuclear antigen, a cell proliferative marker also known as MKI67 has provided a reliable method to estimate tumour intensification rate." (PMID 31983161, 2020).
tumor (continued). "Together, these results indicate that Mtb effector protein PtpA contributes to Mtb-promoted tumor cell proliferation, migration, and invasion, which are partially dependent on MKI67." (PMID 33097805, 2020). "We also observed that the proliferation marker MKI67 was positively stained less frequently in TROJAN knockdown tumor samples than in control tumor samples." (PMID 32393270, 2020). "MKI67 protein quantitation by IHC revealed a generally increased proliferation in heterospheroid tumour cells, demonstrating induction by the stromal compartment (PSCs)." (PMID 32460715, 2020). "The MKI67 labeling index also correlates with tumor growth rates, histologic stage, and tumor recurrence." (PMID 32348423, 2020). "MKi67 is a cell cycle and tumor growth marker presenting only in the nuclei of cycling cells and upregulated in cycling cells." (PMID 30733836, 2019). "In multivariable analysis in the ESR1+/ERBB2- set the MKI67 status and tumor stage displayed almost identical hazard ratios, however only stage was clearly significant." (PMID 31307414, 2019). "The authors also discovered that an increased Ki-67/MKI67 expression was related to Lauren's classification and tumor size." (PMID 31632479, 2019). "In the present study, we firstly investigated the ability of Ki-67/MKI67 in discriminating tumor from normal controls." (PMID 31632479, 2019). "We subsequently conducted fluorescent-immunohistochemical analysis of the xenografted tumor tissues to determine the expression levels of marker of proliferation KI67 (MKI67), as well as TUNEL staining to determine the degree of apoptosis." (PMID 31354472, 2019). "Simultaneously, we investigated the underling action mechanism by which Ki-67/MKI67 affects cell proliferation and promotes tumor development by performing bioinformatics analysis on genes co-expressed with MKI67." (PMID 31632479, 2019). "In line, the RNA seq analysis showed a 2.05 fold (log2FC = 1.04) higher expression of the proliferation marker MKI67 in tumor spheroids upon infiltration with MФs." (PMID 30615637, 2019). "Among these, Mki-67 (ki-67 protein) high expression has long been known to correlate with an exacerbated proliferation rate in the tumour site, hence forming a hostile TME5." (PMID 30996291, 2019). "In line with our in vitro data, tumor samples displayed higher expression of the proliferation marker MKI67 and also contained more MΦ marker MSR1." (PMID 30615637, 2019). "Methylation analysis of the Cdh1, Cdh2, Mmp9, Mki67, Gfap, Gap43, Robo2, and Slit2 genes from tumor samples demonstrated that all of them were methylated in their promoter regions unlike those from normal tissues." (PMID 31921388, 2019). "In vivo, D2A1 tumours have a spindle-cell histology with ∼18% Ki67 (Mki67)-positive cells and ∼20% caspase 3-positive nuclei." (PMID 29208627, 2018). "The levels of cell proliferation marker MKI67 (Ki67) is an important indicator of tumor growth and aggressiveness used for grading NETs." (PMID 29872498, 2018). "MKi67 is a biomarker for tumor proliferation, the Pearson’s correlation of MKi67 and real hub genes were performed." (PMID 30158955, 2018). "MKI67 scores in blood correlate poor with tissue KI-67 because MKI67 is a dynamic tumor product capturing real-time biological variation whereas immunohistochemistry is a static pathological, “one-off” finding." (PMID 30564197, 2018). "Although MKI67 is one of the markers measured by the NETest and both the NETest and tumor grade are independent predictors for disease progression, the absence of an association is not surprising." (PMID 30564197, 2018). "This is the first study to compare tumor MKI67 gene expression by RNA and protein assessment in a prospective retrospective neoadjuvant setting." (PMID 28193205, 2017). "ESR1 (ER), PGR (PR), ERBB2 (HER2) gene expression values tended to be homogeneous across different tumor regions, while MKI67 mRNA levels are slightly varying between regions." (PMID 29187174, 2017).